TMT1B (thiol methyltransferase 1B)
Description:
Thiol S-methyltransferase that catalyzes the transfer of a methyl group from S-adenosyl-L-methionine to alkyl and phenolic thiol-containing acceptor substrates. Together with TMT1B accounts for most of S-thiol methylation activity in the endoplasmic reticulum of hepatocytes. Selectively methylates S-centered nucleophiles from metabolites such as hydrogen sulfide and dithiothreitol.
Synonyms: METTL7B; MGC17301; ALDI
Tractability: Antibody: UniProt places it where antibodies can reach, with medium confidence; UniProt predicts a signal peptide or a membrane-spanning region. PROTAC: ubiquitination databases record sites on it.
Gene: Protein-coding gene on chromosome 12 (55,681,736 to 55,684,611, forward strand). Ensembl gene ENSG00000170439.
Subcellular location: Endoplasmic reticulum membrane; Lipid droplet; Microsome; Cytoplasm, cytosol
Subcellular location (Human Protein Atlas): Microtubules; Vesicles
Gene Ontology:
Molecular function: S-adenosylmethionine-dependent methyltransferase activity; thiol S-methyltransferase activity
Cellular component: endoplasmic reticulum membrane; lipid droplet; cytosol
Genetic constraint (gnomAD): Loss-of-function variants: 8 observed, 12.57 expected, observed/expected ratio (o/e) 0.64, 90% interval 0.37 to 1.15. The upper end of that interval is the gene's LOEUF score, 1.15, which puts it in group 5 of 6, group 1 being the genes least tolerant of losing a copy. Missense variants: 308 observed, 314.03 expected, observed/expected ratio (o/e) 0.98, 90% interval 0.89 to 1.08. Synonymous variants: 111 observed, 124.06 expected, observed/expected ratio (o/e) 0.89, 90% interval 0.77 to 1.05.
Homologues: Orthologues: chimpanzee TMT1B (100% identical), macaque TMT1B (96% identical), dog TMT1B (87% identical), rabbit TMT1B (87% identical), pig TMT1B (84% identical), mouse Tmt1b (84% identical), rat Tmt1b (84% identical), guinea pig TMT1B (83% identical), Caenorhabditis elegans K12D9.1 (14% identical), Caenorhabditis elegans R08F11.4 (14% identical), Caenorhabditis elegans rips-1 (13% identical), Caenorhabditis elegans R08E5.1 (12% identical), and 1 more. Paralogues in human: TMT1A (57% identical), AS3MT (16% identical), METTL27 (16% identical), COQ5 (14% identical).
Diseases named in the same sentence as TMT1B in open-access papers:
TMT1B is named in the same sentence as 34 diseases in open-access papers, as found by Europe PMC text mining. Sharing a sentence is not in itself a finding about the gene and the disease. The quoted sentences say what the papers report.
glioma (11 papers, 2021 to 2025). A benign or malignant brain and spinal cord tumor that arises from glial cells (astrocytes, oligodendrocytes, ependymal cells). "Following the loss of TMT1B expression in thyroid cancer cells, a significant decrease in proliferation was found, similar to effects seen in non-small cell lung cancer, clear cell renal cancer, and glioma cells." (PMID 37456227, 2023). "Wound healing assays in cells depleted of TMT1B showed a profound impairment in cell migration relative to control cells in both lung adenocarcinomas and gliomas." (PMID 37456227, 2023). "Differential expression of TMT1B has been found to occur within several cancer types, including gliomas, non-small cell lung cancer, and acute myeloid leukemia." (PMID 37456227, 2023). "First identified in the stacked Golgi, TMT1B is also localized to the endoplasmic reticulum as well as lipid droplets and has been reported as being upregulated in a wide range of cancer types including lung cancer, gliomas, and leukemia." (PMID 37456227, 2023).
lung adenocarcinoma (9 papers, 2020 to 2026). A carcinoma that arises from the lung and is characterized by the presence of malignant glandular epithelial cells. "Conversely, overexpression of TMT1B in thyroid cancer and lung adenocarcinoma cells significantly promoted cell proliferation." (PMID 37456227, 2023). "Conversely, overexpression of TMT1B in thyroid cancer and lung adenocarcinoma significantly facilitated both migration and invasion." (PMID 37456227, 2023). "Similarly, in TMT1B-ablated lung adenocarcinoma cells, other proliferation-related genes such as PCLAF, CDC20, CDC25B, AURKB, MKI67, BIRC5 and HMGA1/2 were found to be downregulated." (PMID 37456227, 2023).
breast carcinoma (8 papers, 2017 to 2024). "However, this hypothesis may depend on the level of TMT1B expression; while migration and invasion decrease following loss in cancers with high TMT1B expression, cancers with low TMT1B expression (e.g. breast cancer) actually show the opposite effect." (PMID 37456227, 2023).
thyroid cancer (7 papers, 2020 to 2023). "TMT1B ablation was found to inhibit the pro-migratory activity of TGF-β in thyroid cancer cells, where loss of TMT1B inhibited the decrease of E-cadherin and increase of N-cadherin typically seen during TGF-β-induced EMT." (PMID 37456227, 2023).
tumor (21 papers, 2017 to 2026). "TMT1B activity in tumours is also linked to the cell’s ability to migrate and invade surrounding tissues." (PMID 37456227, 2023). "TMT1B’s effect on proliferation has been seen in mouse models as well, with decreases in size and weight of xenograft tumours in BALB/c nude mice following subcutaneous implementation of TMT1B-silenced cells." (PMID 37456227, 2023). "TMT1B has been proposed as a biomarker for many of these cancers since its increased transcription and protein abundance is frequently correlated with an advanced TNM (Tumour, Node, Metastasis) stage of tumour development and poor patient overall survival, risk of recurrence and drug resistance." (PMID 37456227, 2023). "At the same time, very few studies have conducted detailed studies of the subcellular movement of TMT1B, and none have been performed in the context of normal versus cancerous cells to elucidate whether its overexpression might lead to an aberrant localization and function specific to tumours." (PMID 37456227, 2023).
cancer (15 papers, 2020 to 2024). A tumor composed of atypical neoplastic, often pleomorphic cells that invade other tissues. "Several studies investigating TMT1B’s effects have highlighted a role in the regulation of cell proliferation in cancer cells." (PMID 37456227, 2023). "A summary of cancers in which TMT1B activity is investigated with an interest in the effects of TMT1B expression on proliferation and migration." (PMID 37456227, 2023). "In this review we summarize the findings of several functional and biochemical studies of TMT1B to provide a comprehensive view of its activity and potential insight into its role in different cancers." (PMID 37456227, 2023). "Despite these characterizations, the exact substrate of TMT1B, and its role in the various cancers where it is highly expressed, have not yet been defined." (PMID 37456227, 2023).
TMT1B also shares sentences with these, for which no sentence is quoted: lung carcinoma (7 papers); non-small cell lung carcinoma (6); glioblastoma (3); low grade glioma (2); papillary thyroid cancer (2); Sepsis (2); acute lymphoblastic leukemia (1); acute respiratory distress syndrome (1); adenocarcinoma (1); asthma (1); clear cell renal cell carcinoma (1); diabetic cardiomyopathy (1); endotoxemia (1); heart failure (1); hepatocellular carcinoma (1); infection (1); leukemia (1); Lymph node metastasis (1); malaria (1); melanoma (1); non-alcoholic steatohepatitis (1); paraganglioma (1); pheochromocytoma and (1); preeclampsia (1); renal carcinoma (1); rheumatoid arthritis (1); Salmonella Infections (1); Yersinia infection (1).